LINC03126 (long independently transcribed non-coding RNA 3126)
Gene: Long non-coding RNA gene on chromosome 1 (16,870,945 to 16,883,659, forward strand). Ensembl gene ENSG00000228549.
Gene Ontology:
Molecular function: pre-mRNA 5'-splice site binding; triplet codon-amino acid adaptor activity
Biological process: mRNA 5'-splice site recognition; translation
Cellular component: U1 snRNP